UICLM (up-regulated in colorectal cancer liver metastasis)
Synonyms: CROCC2-AS1
Gene: Long non-coding RNA gene on chromosome 2 (240,954,617 to 240,967,451, reverse strand). Ensembl gene ENSG00000233392.
Diseases named in the same sentence as UICLM in open-access papers:
UICLM is named in the same sentence as 13 diseases in open-access papers, as found by Europe PMC text mining. Sharing a sentence is not in itself a finding about the gene and the disease. The quoted sentences say what the papers report.
colorectal cancer (14 papers, 2018 to 2025). A primary or metastatic malignant neoplasm that affects the colon or rectum. "The lncRNA UICLM (upregulated in colorectal cancer liver metastasis) regulates zinc finger E-box binding homeobox 2 (ZEB2) expression by acting as a ceRNA of microRNA-215, thereby promoting liver metastasis of colorectal cancer." (PMID 33558499, 2021). "UICLM promoted colorectal cancer metastasis by acting as a ceRNA which sponges miRNA-215 to regulate ZEB2 expression." (PMID 33658048, 2021). "For instance, lncRNA UICLM functions as a ceRNA in colorectal cancer and promotes its liver metastasis by regulating miRNA-215/ZEB2 axis." (PMID 32231464, 2020). "UICLM regulates the expression of miRNA-215 by acting as a ceRNA, thereby promoting the metastasis of colorectal cancer." (PMID 32163372, 2020). "As an example, UICLM promotes the metastasis of colorectal cancer by serving as a ceRNA of ZEB2 via interacting with microRNA-215." (PMID 32110804, 2020). "In colorectal cancer, lncRNA UICLM is a competitive endogenous RNA (ceRNA) that binds to miR-215 and suppresses the inhibition of ZIR2 by miR-215, thereby playing a role in promoting liver metastasis of colon cancer." (PMID 30836987, 2019). "For instance, in colorectal cancer, lncRNA UICLM acts as a ceRNA for miR-215 to regulate ZEB2 expression and promote colorectal cancer metastasis." (PMID 30098599, 2018). "For example, UICLM, LINC00657 and SNHG15 were reported to facilitate cancer development via serving as miRNAs sponges in colorectal carcinoma, esophageal squamous cell carcinoma and papillary thyroid carcinoma." (PMID 32976115, 2020). "A previous report demonstrated that lncRNA UICLM (upregulated in colorectal cancer liver metastasis) expression in CRC promoted tumor growth and liver metastasis, and knockdown of lncRNA UICLM expression impaired cell sphere-forming ability and epithelial-mesenchymal transformation (EMT)." (PMID 32690100, 2020).
COVID-19 (1 paper, 2021). A disease caused by infection with severe acute respiratory syndrome coronavirus 2. "Interestingly we found six lncRNAs (TALAM1, DLEU2, and UICLM CASC18, SNHG20, and GNAS) involved in the protein-coding DEG-lncRNA network; which might be served as potential biomarkers for COVID-19 patients." (PMID 34975833, 2021).
tumor (8 papers, 2020 to 2024). "The clinical stage of CRC patients was associated with an increase in the expression level of the lncRNA UICLM in tumor tissues." (PMID 38294554, 2024). "At the same time, the expression of UICLM in tumor tissues of patients with liver metastases was significantly higher than that without liver metastases." (PMID 36797749, 2023). "For example, Chen’s study reported that: the later the clinical stage of CRC patients, the higher the expression level of lncRNA UICLM in the tumor tissues." (PMID 36797749, 2023). "Higher levels of UICLM were significantly correlated with CRC larger tumor size, advanced tumor stage as well as liver metastasis." (PMID 36229883, 2022). "Therefore, UICLM expression in tumor tissues can be used as a potential predictor of tumor stage and liver metastasis." (PMID 36797749, 2023). "In addition, individuals with liver metastases had considerably higher levels of UICLM expression in their tumor tissues than patients without liver metastases." (PMID 38294554, 2024).
cancer (4 papers, 2019 to 2023). A tumor composed of atypical neoplastic, often pleomorphic cells that invade other tissues. "Taken together, UICLM is a promising therapeutic target since the knockdown of UICLM not only negatively regulates ZEB2, but also markedly inhibits stemness-related genes such as SOX2, Notch1, and cancer stem cell (CSC)-associated surface antigens, such as CD44 and CD24." (PMID 31744051, 2019).
UICLM also shares sentences with these, for which no sentence is quoted: hepatocellular carcinoma (2 papers); breast carcinoma (1); colon cancer (1); esophageal squamous cell carcinoma (1); gastric cancer (1); pancreatic cancer (1); papillary thyroid carcinoma (1); renal cell carcinoma (1); serous ovarian cancer (1).